IL6 (interleukin 6)
Diseases named in the same sentence as IL6 in open-access papers (continued):
Sharing a sentence is not in itself a finding about the gene and the disease.
Insulin resistance (continued). "In obese subjects, infiltrated macrophages together with enlarged adipocytes secrete numerous pro-inflammatory mediators such as IL-6 and TNF-α, which contribute to insulin resistance." (PMID 20735814, 2010). "The use of TZDs in the treatment of T2D improves insulin resistance by increasing GLUT-4 levels and decreasing the levels of cytokines that induce insulin resistance, such as TNF-α and IL-6 by antagonizing the activity of proinflammatory transcription factors." (PMID 19746174, 2010). "However, application of IL6 to healthy volunteers recently failed to cause insulin resistance in humans and was even associated with improved muscular glucose disposal and decreased endogenous glucose production, which was attributed to IL6 dependent activation of AMPK." (PMID 19087258, 2008). "Recent results from the INCHIANTI population study showed that subjects in the upper tertile of insulin resistance had increased serum levels of TNF-α, IL-1R antagonist and IL-6 and low levels of sIL-6R." (PMID 15904534, 2005). "In the T2D model, TH mice exhibited more severe hyperglycemia, insulin resistance, and β‐cell dysfunction than TN mice, accompanied by increased hepatic TNF‐α and IL‐6 expression, enhanced lipid accumulation, suppressed IRS‐1 phosphorylation, and enhanced JNK and IKKβ phosphorylation." (PMID 41388732, 2026). "In experimental animals, adipokines such as TNF-α, IL-6, Retinal binding protein-4 (RBP4), IL-18, lipocalin 2, as well as BCAA levels are linked to insulin resistance, although there is little evidence in humans." (PMID 39791169, 2025). "It has been well-documented that insulin resistance results in elevated levels of inflammatory factor markers, such as C-reactive protein (CRP) and cytokine interleukin 6 (IL-6), and promotes adverse outcomes of atherothrombosis through an acceleration of the premature atherosclerosis process." (PMID 40313489, 2025). "Under conditions of insulin resistance, the secretion of pro-inflammatory cytokines, such as TNF-α and IL-6, is elevated, which may worsen chronic intestinal inflammation." (PMID 40936909, 2025). "At higher WWI values, increased visceral fat may trigger early insulin resistance, endothelial dysfunction, and elevated pro-inflammatory cytokines (e.g., TNF-α, IL-6), exacerbating renal microvascular injury and protein leakage." (PMID 40700436, 2025). "Elevated IL-6 levels can directly impair pancreatic β-cell function and increase hepatic glucose production, while high CRP levels indicate systemic inflammation, which contributes to insulin resistance." (PMID 41523554, 2025). "MetS is characterized by caloric excess, insulin resistance, and dyslipidemia, which promote adipocyte hypertrophy, local hypoxia, and HIF-1α–driven low-grade inflammation with TNF-α, IL-6 and MCP-1 signaling, engaging NF-κB/JAK–STAT pathways and worsening insulin resistance." (PMID 41409612, 2025). "Even in eutrophic adolescents, but with a high %BF, IL-6 was correlated with other inflammatory cytokines, such as TNF-α and with the development of insulin resistance as well as, with modulating the synthesis of CRP, showing the role of adipose tissue in inflammation." (PMID 40717997, 2025). "Chronic low-grade inflammation, characterized by persistent elevation of pro-inflammatory cytokines (e.g., IL-6, TNF-α), and metabolic syndrome components, including insulin resistance, hypertension, and dyslipidemia, have been identified as shared risk factors for both conditions." (PMID 40356818, 2025). "Chronic hyperglycemia, insulin resistance, and lipid abnormalities can also induce a persistent inflammatory state, triggering excessive release of pro-inflammatory cytokines such as TNF-α and IL-6." (PMID 40260393, 2025).
Insulin resistance (continued). "Inflammation-wise, the majority of the studies emphasized the ability of anthocyanins to reduce pro-inflammatory cytokines such as IFN-γ, IL-6, TNF-α, and MCP-1 that have a tendency to be elevated in obesity and contribute to insulin resistance and metabolic abnormalities." (PMID 40218884, 2025). "The study concluded that PCOS patients with insulin resistance exhibited significantly higher levels of IL-6 compared to those without insulin resistance, suggesting a strong correlation between IL-6 levels and insulin resistance in the context of PCOS." (PMID 40226143, 2025). "Increased gut permeability, promoted neutrophil infiltration, and increased levels of IL-6, IL-1β, and TNF-α, and increased skeletal muscle insulin resistance and inflammation via simulating PPAR-δ are some suggested mechanisms attributed to simple sugar intake." (PMID 39974842, 2025). "Key metabolic and inflammatory markers such as insulin resistance, C-reactive protein, and interleukin-6 were not measured." (PMID 40688878, 2025). "Blood samples were collected before and after the exercise to measure fasting blood sugar (FBS), insulin, Homeostatic Model Assessment of Insulin Resistance (HOMA-IR), IL-6, and fractalkine levels, allowing for an assessment of the exercise's effects on both groups." (PMID 40091956, 2025). "Inflammatory cytokines, such as tumor necrosis factor-alpha (TNF-α), interleukin-6 (IL-6), IL-1β, IL-1, IL-17, and monocyte chemoattractant protein-1 (MCP-1), contribute to the advancement of NAFLD by fostering insulin resistance, hepatic inflammation, and fibrosis." (PMID 41257640, 2025). "IL-6 and CRP increase during inflammation, impacting glucose metabolism through insulin resistance." (PMID 41404504, 2025). "When compared to IL-6, TNF-α appears to have a more direct effect on insulin resistance." (PMID 40385768, 2025). "Mechanistically, it promotes inflammation via IL-6, TNF-α, and IL-1β and may contribute to insulin resistance." (PMID 41464844, 2025). "These cytokines and chemokines, including tumor necrosis factor-alpha (TNF-α), interleukin-6 (IL-6), and monocyte chemoattractant protein-1 (MCP-1), contribute to endothelial dysfunction, insulin resistance, and renal impairment, all of which disrupt electrolyte homeostasis." (PMID 40136609, 2025). "Increased levels of tumor necrosis factor-alpha (TNF-α), interleukin-6 (IL-6), and C-reactive protein (CRP) contribute to insulin resistance, oxidative stress, and enhanced cellular proliferation, creating a microenvironment conducive to CRC development and progression." (PMID 40444236, 2025). "Studies have demonstrated that berberine enhances lipid metabolism, lowers LDL-C, TG, and TC levels, improves insulin resistance and oxidative stress, and exerts anti-inflammatory effects through the inhibition of TNF-α and IL-6 secretion, as well as modulation of the PPARγ signaling pathway." (PMID 41304686, 2025). "Insulin resistance reduces nitric oxide (NO) bioavailability, promoting vasoconstriction and vascular stiffness, while also enhancing the production of pro-inflammatory cytokines, including TNF-α and IL-6, further accelerating vascular damage." (PMID 40839683, 2025). "In fact, it was shown that the pro-inflammatory cytokines IL-6, MCP-1, IL-1β, and TNF-α secreted by hypertrophic adipose tissue in obese individuals can disrupt insulin signalling and promote insulin resistance, contributing to the pathophysiology of diabesity." (PMID 41155431, 2025). "In scenarios of insulin resistance, low-grade inflammation plays a prominent role in the dysfunction of insulin signaling, mainly through cytokines like tumor necrosis factor-alpha (TNF-α) and interleukin-6 (IL-6)." (PMID 40563357, 2025).
Insulin resistance (continued). "This microenvironment promotes the secretion of cytokines, such as TNF-α and IL-6, which impair insulin signaling by inhibiting the IRS-1/PI3K/Akt pathway, contributing substantially to the systemic insulin resistance observed in the Ob-Veh and HE-Ob-Veh groups." (PMID 41471698, 2025). "On one hand, periodontal disease triggers the release of inflammatory cytokines, such as interleukin-6 (IL-6) and tumor necrosis factor-alpha (TNF-α), which impair insulin signaling pathways, resulting in increased insulin resistance and poor glycemic control in diabetic patients." (PMID 40283848, 2025). "The combined intervention (EDG) reduced the insulin resistance FG/I (p = 0.02) and atherogenic index CRI II (p = 0.01), decreased inflammatory markers IL-6 (p = 0.01) by 48% and hs-CRP (p = 0.04) by 30%, and simultaneously increased the ADIPO (p = 0.02) concentration by 15%." (PMID 41096768, 2025). "These stressors activate key inflammatory pathways such as Nuclear Factor kappa-light-chain-enhancer of activated B cells (NF-κB) in the liver, promoting the production of pro-inflammatory cytokines like IL-6, IL-1β, and TNF-α, which together foster insulin resistance and low-grade inflammation." (PMID 40564033, 2025). "Adipose tissue exosomes can also modulate macrophage activation and the production of proinflammatory cytokines such as IL-6 and TNF-α via increased obese adipose exosomal miR-34a’s, which inhibits M2 polarization and positively correlates with insulin resistance." (PMID 40696355, 2025). "The major mechanisms of insulin resistance in CKD are thought to involve pro-inflammatory cytokines such as tumor necrosis factor-α (TNF-α), interleukin-6 (IL-6), and interferon-γ (IFN-γ), which inhibit phosphorylation of the insulin receptor and insulin receptor substrate-1 (IRS-1)." (PMID 41157262, 2025). "Most studies reported statistically significant reductions in multiple key inflammatory mediators, particularly TNF-α, IL-6, IL-1β, and CRP, which are central to the pathophysiology of insulin resistance, adipose tissue dysfunction, and cardiovascular complications in metabolic syndrome." (PMID 40868165, 2025). "Additionally, tumor cells can secrete large amounts of IL-6 and TNF-α, leading to insulin resistance and subsequent hyperglycemia." (PMID 39687887, 2024). "Additionally, insulin resistance induces chronic low-grade inflammation, characterized by elevated cytokines such as TNF-α and IL-6, further accelerating GC progression." (PMID 39736510, 2024). "However, VAT particularly displays a major role in insulin resistance and TNF, IL-6 mediated adipose tissue inflammation." (PMID 39728000, 2024). "Chronic inflammation marked by elevated IL-6 disrupts systemic metabolism, activating other pro-inflammatory cytokines like TNF-α and IL-1, creating a feedback loop that intensifies inflammation and insulin resistance." (PMID 39857603, 2024). "Additionally, TNFα and IL-6 enhance PAI-1 and TF in adipose tissue, further exacerbating the procoagulant state, insulin resistance, and MCP-1 production from adipocytes and endothelial cells in adipose tissue." (PMID 39858414, 2024). "In diabetes, elevated IL-6 exacerbates oxidative stress by upregulating NADPH oxidase activity and ROS production, particularly in adipose and muscle tissues, contributing to systemic inflammation and insulin resistance." (PMID 39857603, 2024). "This is primarily caused by the generation of pro-inflammatory cytokines including interleukin-6 (IL-6) and tumor necrosis factor-α (TNF-α), which have significant metabolic effects on insulin resistance and lipid metabolism in addition to inducing inflammation." (PMID 39872862, 2024). "Moreover, insulin resistance increases circulating pro-inflammatory cytokines, such as TNF-α and IL-6, through exacerbated oxidative stress." (PMID 39125385, 2024).
Insulin resistance (continued). "CRP, fibrinogen, and ESR were useful, but more specific investigations into aspects such as IL-6 and TNF-α may be necessary to better understand the role of insulin resistance in MetS." (PMID 38731059, 2024). "The development of insulin resistance is significantly impacted by inflammation, and in this study, BPA-induced insulin resistance correlates with increased TNF-α and IL6 production, suggesting a connection between inflammation, diabetes, and pancreatic islet dysfunction." (PMID 38580733, 2024). "Furthermore, LrB can reduce inflammation and insulin resistance in individuals with PCOS by inhibiting NLRP3, Caspase-1, TNF-α, IL-6, IL-1β, and IL-18 and increasing the expressions of GPR120, LKB1, and AMPK." (PMID 39456928, 2024). "Among the other factors we examined—total fat, subcutaneous fat, insulin resistance, and interleukin-6 (IL-6)—none had an impact on fatigue levels." (PMID 39200888, 2024). "Insulin resistance in patients with RA may be attributed to the increase in proinflammatory cytokines like TNF-α and IL-6 and the extensive use of GCs during the pandemic, especially for patients with low SpO2 levels." (PMID 39456932, 2024). "The elevation of circulating IL6 and IL8 levels in obese individuals may be more likely related to T2D and insulin resistance." (PMID 38541912, 2024). "Similarly, persistent elevation of IL-6 and TNF-α, released by adipocytes and muscle cells, can lead to the progression of insulin resistance and subsequently contribute to the onset of metabolic diseases." (PMID 39335642, 2024). "By inhibiting pro-inflammatory cytokines such as interleukin-6 (IL-6) and tumor necrosis factor-alpha (TNF-α), SB could reduce chronic inflammation, a key factor in insulin resistance and atherosclerosis." (PMID 39590851, 2024). "TNF-α, IL-6, and leptin activate inhibitory molecules such as the suppressor of cytokine signaling 3 (SOCS3) and c-Jun NH2-terminal kinase (JNK) that suppress insulin signaling, thus resulting in insulin resistance." (PMID 38397916, 2024). "An inflamed visceral fat pad produces pro-inflammatory adipokines including interleukin-1β (IL-1β), interleukin-6 (IL-6), and tumor necrosis factor-α (TNF-α), which contribute to the progression of systemic insulin resistance, type 2 diabetes, MAFLD, heart failure, and atherosclerosis." (PMID 39160276, 2024). "In individuals with NAFLD, lipotoxicity, insulin resistance, and endotoxins trigger the activation of proinflammatory cytokines such as tumor necrosis factor-α (TNF-α), interleukin-1α (IL-1α), interleukin-1β (IL-1β), interleukin-6 (IL-6), and resistin." (PMID 39275255, 2024). "PTSD is associated with elevated levels of inflammatory markers, including CRP, interleukin-6 (IL-6), and tumor necrosis factor-alpha (TNF-α), that could exacerbate insulin resistance." (PMID 38646205, 2024). "TNF-α, IL-6, IL-1β, and HOMA-IR were significantly lower in the semaglutide-treated group, suggesting that semaglutide has a beneficial effect on muscle function by reducing the inflammatory response and insulin resistance." (PMID 39125786, 2024). "Circadian rhythm dysfunction promotes the secretion of inflammatory cytokines (TNFα, IL-1β, and IL-6), which induces insulin resistance and makes a negative effect on the production of GnRH and LH." (PMID 37229470, 2023). "In addition, brown adipose tissue releases pro-inflammatory mediators such as IL-8, IL-4, IL-1, IL-6, TNF-α, and histamine in response to high blood glucose levels and improved insulin resistance." (PMID 37241737, 2023). "At the same time, key substances and signalling pathways affecting insulin resistance have been identified, such as insulin receptor substrate (IRS), tumour necrosis factor-α (TNF-α), interleukin-6 (IL-6), protein tyrosine phosphatase 1B (PTP1B), PI3K-Akt, ERK, and adipocytokines." (PMID 37089923, 2023).
Insulin resistance (continued). "Insulin resistance and hyperinsulinemia promote the production of pro-inflammatory cytokines such as tumor necrosis factor-alpha (TNF-α) and interleukin-6 (IL-6), leading to increased oxidative stress and impaired nitric oxide (NO) bioavailability, which in turn promotes endothelial dysfunction." (PMID 37367870, 2023). "In addition, metabolic parameters such as insulin, triglyceride, Homeostatic Model Assessment of Insulin Resistance (HOMA-IR), low-density lipoprotein (LDL), interleukin 6 (IL-6), and leptin have also been found to be negatively related to RNFL thickness." (PMID 37033164, 2023). "This leads to peripheral insulin resistance and impairment of pancreatic β-cell insulin secretion, while the adipocytes elevate adipokine secretion, NGF, interleukin 6 (IL-6), IL-1, tumor necrosis factor-α (TNF-α), and monocyte chemoattractant protein-1 (MCP-1)." (PMID 37373824, 2023). "Interleukin-6 (IL-6), Interleukin 1-β (IL1-β), and tumor necrosis factor α (TNFα) increase local and systemic inflammation, recruit macrophages, and alter insulin signaling to promote insulin resistance." (PMID 37443781, 2023). "We found that JAZF‐1 and PPAR‐γ could promote Tregs differentiation and regulate insulin resistance by synergistically decreasing the expression levels of TNF‐α, IL‐1β and IL‐6 and increasing those of IL‐10 and TGF‐β." (PMID 36734198, 2023). "Brain insulin resistance occurs through the release of pro-inflammatory cytokines; peripherally produced pro-inflammatory cytokines such as TNF-α, IL-6, IL-12 and IL-1β can cross the blood-brain barrier, leading to neuroinflammation and central insulin resistance." (PMID 37415663, 2023). "Thus, it is not surprising that key proinflammatory cytokines, including TNF-a, IL-6, CCL2, and CCL5, which are present at high serum concentrations in patients with insulin resistance, are mediators of HSC activation." (PMID 37735474, 2023). "The expression of interleukin-6 (IL-6), neuronal (n), and inducible isoform (i) nitric oxide synthases (NOS) was investigated for their important role in inflammation, vascularization, stress, and insulin resistance." (PMID 37888177, 2023). "Moreover, IL-6 increases the expression of the suppressors of cytokine signaling (SOCS) 1 and SOCS3, leading to the degradation of IRS-1 and the development of insulin resistance." (PMID 37876013, 2023). "Inflammatory cytokines, such as interleukin-1 (IL-1), interleukin-6 (IL-6), and tumour necrosis factor-α (TNF-α), suppress insulin release and induce insulin resistance, and elevated levels of IL-6 promote hyperglycaemia by releasing glucose from hepatic glycogen reserves." (PMID 38255162, 2023). "Although the directionality of the association between MAFLD and psoriasis has not been clearly determined, the excess production of pro-inflammatory cytokines produced by lymphocytes and keratinocytes present in psoriatic skin (e.g., IL-6, TNF-α, IL-17) are believed to mediate insulin resistance." (PMID 36836776, 2023). "Taken together, these studies present the tantalizing but still unproven hypothesis that IL-6 and TNF-α in conjunction directly modulate insulin resistance, androgen excess, and ovulatory dysfunction in PCOS." (PMID 37195871, 2023). "In another cited study, IL-6 was administered continuously in a mouse model without any liver injury, and biochemical features of insulin resistance were observed immediately after cessation of IL-6 supplementation for 5 to 7 days." (PMID 37593740, 2023). "Despite the inter-relationship between IL-6, TNF-α and CRP, this study neither found similar associations between IL-6 and TNF-α with insulin resistance nor with other metabolic outcomes." (PMID 37891561, 2023). "In women, plasma CNTF showed a moderate correlation with WHR; notably, there was a strong correlation with BMI, the insulin resistance indices fasting insulin and HOMA index and the inflammatory markers hsCRP and IL-6, as well as a very strong correlation with leptin." (PMID 35585213, 2022).